POC1A (POC1 centriolar protein A)
Description:
Plays an important role in centriole assembly and/or stability and ciliogenesis. Involved in early steps of centriole duplication, as well as in the later steps of centriole length control. Acts in concert with POC1B to ensure centriole integrity and proper mitotic spindle formation.
Synonyms: WDR51A; DKFZP434C245; PIX2; SOFT
Tractability: PROTAC: ubiquitination databases record sites on it.
Gene: Protein-coding gene on chromosome 3 (52,074,590 to 52,154,735, reverse strand). Ensembl gene ENSG00000164087.
Subcellular location: Cytoplasm, cytoskeleton, microtubule organizing center, centrosome; Cytoplasm, cytoskeleton, microtubule organizing center, centrosome, centriole; Cytoplasm, cytoskeleton, cilium basal body; Cytoplasm, cytoskeleton, spindle pole
Subcellular location (Human Protein Atlas): Flagellar centriole; Mid piece; Principal piece
Gene Ontology:
Molecular function: protein binding
Biological process: cilium assembly
Cellular component: centriole; centrosome; ciliary basal body; spindle pole; cytoplasm
Genetic constraint (gnomAD): Loss-of-function variants: 25 observed, 35.33 expected, observed/expected ratio (o/e) 0.71, 90% interval 0.51 to 0.99. The synonymous counts are far from expectation, so gnomAD's model fits this gene poorly and the ratio says little. Missense variants: 378 observed, 451.68 expected, observed/expected ratio (o/e) 0.84, 90% interval 0.77 to 0.91. Synonymous variants: 142 observed, 182.01 expected, observed/expected ratio (o/e) 0.78, 90% interval 0.68 to 0.9.
Homologues: Orthologues: macaque POC1A (98% identical), pig POC1A (93% identical), rabbit POC1A (92% identical), guinea pig POC1A (91% identical), chimpanzee POC1A (91% identical), mouse Poc1a (90% identical), rat Poc1a (90% identical), dog POC1A (88% identical), tropical clawed frog poc1a (71% identical), zebrafish poc1a (28% identical). Paralogues in human: POC1B (57% identical), WDR17 (26% identical), TEP1 (25% identical), WDR5 (23% identical), WDR5B (23% identical), PAFAH1B1 (20% identical), AHI1 (19% identical), WDR7 (19% identical), SNRNP40 (19% identical), WDR62 (19% identical), MAPKBP1 (18% identical), WDR27 (18% identical), and 14 more.
Diseases named in the same sentence as POC1A in open-access papers:
POC1A is named in the same sentence as 37 diseases in open-access papers, as found by Europe PMC text mining. Sharing a sentence is not in itself a finding about the gene and the disease. The quoted sentences say what the papers report.
primordial dwarfism (4 papers, 2015 to 2017). "Poc1a and several other genes associated with centrosome function can affect the skeleton and lead to skeletal dysplasias and primordial dwarfisms." (PMID 26496357, 2015). "For example, a form of primordial dwarfism was found to be caused by mutations in the gene encoding the major centriolar protein POC1A." (PMID 25361962, 2015). "Other genes associated with microcephalic primordial dwarfism shown to cause defects in centrosomal and spindle microtubule function include: PCNT, CENPE and POC1A." (PMID 28334956, 2017). "WDR51A (WD repeat domain 51A), also known as POC1A (centriolar protein A) have been found to show mutations in the centrosomal gene for individuals with primordial dwarfism and extreme insulin resistance." (PMID 29084944, 2017).
SOFT syndrome (4 papers, 2019 to 2024). "This study confirms that severe IR is a prominent feature of SOFT syndrome related to biallelic POC1A variants." (PMID 39017987, 2024). "This systematic study confirmed that the severe short stature was a major feature of SOFT syndrome related to biallelic POC1A variants, present in all affected individuals described to date." (PMID 39017987, 2024). "SOFT syndrome (Short stature-Onychodysplasia-Facial dysmorphism-hypoTrichosis) is a rare primordial dwarfism syndrome caused by biallelic variants in POC1A encoding a centriolar protein." (PMID 39017987, 2024). "Addressing this experimentally will be challenging due to the numerous functions of the centrosome, but the viability of mice with Poc1a deficiency, which recapitulate skeletal manifestations of SOFT syndrome, will permit future studies." (PMID 35234134, 2022). "In Case 1 a rare homozygous POC1A missense variant (c.649C>T, p.(Arg217Trp)) was found, as previously reported in a Chilean girl with SOFT syndrome." (PMID 35234134, 2022). "Here, we report the first Chinese patient of SOFT syndrome harboring a homozygous splicing variant of POC1A gene." (PMID 34419044, 2021). "Contrary to a previous hypothesis stating that the phenotype of severe IR associated with SOFT syndrome could be linked to frameshift POC1A variants affecting exon 10, IR was present regardless of the position of variants in this systematic review." (PMID 39017987, 2024). "Pathogenic variants in POC1A led to SOFT syndrome and variant POC1A-related (vPOC1A) syndrome." (PMID 34419044, 2021). "SOFT syndrome is caused by POC1A gene mutation and is inherited in an autosomal recessive manner." (PMID 34419044, 2021). "Our study enriched mutational spectrum of POC1A which could help in further genetic diagnosis and counselling of SOFT syndrome patients." (PMID 34419044, 2021). "In conclusion, patients with SOFT syndrome often manifest severe dyslipidaemic IR and muscle cramps, independent of the position of the POC1A variant." (PMID 35234134, 2022). "As these radiological signs are not specific for SOFT syndrome, genetic investigations should include the analysis of the POC1A gene in patients with short stature and skeletal involvement." (PMID 39017987, 2024).
ciliopathy (3 papers, 2014 to 2024). A genetic disorder of the cellular cilia or the cilia anchoring structures, the basal bodies, or of ciliary function. "In order to shed light on this novel ciliopathy, we conducted a systematic review of the literature to describe the phenotypic spectrum of POC1A deficiency, focusing on the characteristics of short stature and metabolic features, and identify potential genotype–phenotype correlations." (PMID 39017987, 2024). "Notably, human ciliopathy mutations in POC1A or POC1B map to the WD40 repeats." (PMID 30741631, 2019). "Human mutations of either paralog, POC1A or POC1B, cause ciliopathy-like pathologies." (PMID 30741631, 2019). "Depletion studies show that POC1B, unlike POC1A, is necessary for ciliogenesis, and typical ciliopathy-associated developmental defects (e.g., curved body axis, kidney cysts, and laterality defects) were described in poc1b morphant zebrafish." (PMID 25018096, 2014).
gastric cancer (3 papers, 2020 to 2022). A primary or metastatic malignant neoplasm involving the stomach. "Chromosome deletion of POC1A was the most marked in gastric cancer, and chromosome amplification was the most significant in seminoma." (PMID 35748773, 2022). "POC1A that takes part in the formation of centrioles, and plays a role in ciliogenesis, was found to be correlated with lymphatic metastasis in gastric cancer." (PMID 36338962, 2022). "The effect of POC1 centriolar protein A (POC1A) on gastric cancer (GC) has not been clearly defined." (PMID 33052878, 2020).
hypotrichosis (3 papers, 2019 to 2025). A congenital condition, usually due to genetic aberrations, that is characterized by a lack of hair growth on the head and/or body. "Many studies have shown that POC1A is associated with short stature, onychodysplasia, facial dysmorphism and hypotrichosis (SOFT) syndrome, which is related to abnormalities in cell mitosis." (PMID 33052878, 2020). "As the core component of the centrosome, POC1A is regarded as a factor that regulates the cell cycle; mutation of POC1A can lead to abnormal mitotic mechanics, multipolar spindles and impaired ciliogenesis which can induce short stature, onychodysplasia, facial dysmorphism, and hypotrichosis (SOFT)." (PMID 33052878, 2020).
male infertility (3 papers, 2015 to 2021). The inability of the male to effect fertilization of an ovum after a specified period of unprotected intercourse. "A loss of function of Poc1a causes skeletal dysplasia and male infertility in chagun mice." (PMID 26496357, 2015). "Male infertility is also frequent amongst PCD patients and mouse models deficient for genes involved in the generation or function of motile cilia, such as Poc1a or Cfap54, showed impaired spermatogenesis and male infertility." (PMID 29245899, 2017). "In mice, expression of Poc1a is enriched in the seminiferous tubules and Sertoli cells, and LINE-retrotransposon mediated deletion of Poc1a (chagun mice) mimic the human disorder and results in male infertility, due to defective meiosis in germ cells." (PMID 33665191, 2021).
breast carcinoma (2 papers, 2019 to 2025). "The survival analysis demonstrated that elevated POC1A expression was obviously linked with poor breast cancer prognosis in TNBC patients." (PMID 40830747, 2025). "Our findings revealed a significant elevation of POC1A expression in breast cancer cells compared to MCF10A, with the highest expression observed in TNBC." (PMID 40830747, 2025). "In our study, we collected data from breast cancer patients from the GSE21653 dataset and analyzed the expression state of POC1A between normal tissue and breast cancer tissue." (PMID 40830747, 2025). "However, rescue experiments were not conducted in vivo and at the cellular level to further prove that POC1A can better support POC1A to regulate the proliferation, migration and invasion of breast cancer by affecting STAT3 phosphorylation directly." (PMID 40830747, 2025). "Thus, it can be observed that POC1A expression is obviously increased in TNBC, which is linked to the prognosis and pathological features of breast cancer patients." (PMID 40830747, 2025). "We observed an upregulation of POC1A expression in breast cancer tissues." (PMID 40830747, 2025). "Moreover, our analysis of GSE data confirmed higher POC1A expression in breast cancer tissues in GSE21653, particularly in patients with TNBC." (PMID 40830747, 2025).
diabetes (2 papers, 2023 to 2024). "POC1A should also be considered as a gene involved in monogenic lipodystrophy, IR and/or diabetes in children with short stature." (PMID 39017987, 2024).
Infertility (2 papers, 2015 to 2022). "The expression of POC1A in wild type tibia is consistent with the observed defects in mutant chondrocyte proliferation and expression in wild type male germ cells and Sertoli cells suggests that one or both cell types could be involved in the infertility of male mutants." (PMID 26496357, 2015).
Insulin resistance (2 papers, 2021 to 2022). Increased resistance towards insulin, that is, diminished effectiveness of insulin in reducing blood glucose levels. "POC1A gene has pleiotropic effects, because truncating variants locating in exon 10 could cause variant POC1A-related (vPOC1A) syndrome, whose main clinical features included an extreme dyslipidemia with insulin resistance, acanthosis nigricans and short stature." (PMID 34419044, 2021).
lymph node metastasis (2 papers, 2020 to 2025). "In addition, the association between increased expression of POC1A and the prognosis of patients who have GC with lymph node metastasis indicates that POC1A can be regarded as a significant factor in tumor metastatic progression." (PMID 33052878, 2020). "POC1A expression was positively related to age, lymph node metastasis, and pathologic stage." (PMID 40830747, 2025). "Further analyses revealed that POC1A was highly expressed, and poor OS in TNBC was observed in lymph node metastasis patients." (PMID 40830747, 2025). "The results exhibited that the POC1A had higher expression in TNBC patients with lymph node metastasis compared to TNBC patients without lymph node metastasis." (PMID 40830747, 2025). "The results suggested that patients in the N0 group, who had no lymph node metastasis, had higher POC1A mRNA expression than patients in the N1-3 group." (PMID 33052878, 2020). "High POC1A expression in patients without lymph node metastasis indicated that POC1A may act as a suppressor of lymph node metastasis in GC." (PMID 33052878, 2020).
ovarian carcinoma (2 papers, 2019 to 2022). A malignant neoplasm originating from the surface ovarian epithelium. "Among candidate gene set, POC1A and SNX13 have limited information on their association with ovarian cancer." (PMID 36338962, 2022). "As a result, six genes (CDT1, CNIH4, CRLS1, LIMCH1, POC1A, and SNX13), and two miRNAs (mir-147a, and mir-103a-3p) were suggested as novel candidate prognostic biomarkers for ovarian cancer." (PMID 36338962, 2022).
stomach adenocarcinoma (2 papers, 2020 to 2022). "We observed the highest frequency of POC1A alterations (>7%) in patients with undifferentiated stomach adenocarcinoma, where “Mutation” was the major type." (PMID 35748773, 2022). "According to the TIMER database, multiple types of copy number alterations (CNAs) of POC1A, especially the POC1A deletion, had significant correlations with the infiltration levels of several immune cells in stomach adenocarcinoma." (PMID 33052878, 2020).
breast adenocarcinoma (1 paper, 2022). "Low nucleosome occupancy that corresponds to large nucleosome-free regions were detected at TSSs of CDT1, CRLS1, and SNX13 in chronic myelogenous leukemia cells, and at TSSs of POC1A, and CRLS1in breast adenocarcinoma cells." (PMID 36338962, 2022).
Hepatic steatosis (1 paper, 2024). Steatosis is a term used to denote lipid accumulation within hepatocytes. "Using POC1A-deleted human adipose stem cells, we have shown that the lack of POC1A protein expression impairs adipocyte differentiation, and induces cellular senescence, which are well-known mechanisms leading to lipodystrophic diseases with IR, hypertriglyceridemia and hepatic steatosis." (PMID 39017987, 2024).
lung carcinoma (1 paper, 2024). "In cell experiments, si‐POC1A was applied to effectively knock down POC1A expression in A549 and H1299 cell lines, aiming to assess the impact of POC1A on lung cancer cell function." (PMID 38429900, 2024). "Cell experiments were conducted to validate the effect of POC1A expression on the proliferation, migration and invasion of lung cancer cells." (PMID 38429900, 2024). "RT‐qPCR results confirmed the effective knockdown of POC1A expression in lung cancer cell lines by si‐POC1A." (PMID 38429900, 2024). "In vitro experiments confirmed that POC1A knockdown led to decreased proliferation, migration, and invasion of lung cancer cells." (PMID 38429900, 2024). "Subsequently, Transwell and wound healing assays were utilized to evaluate the influence of POC1A on lung cancer cell migration, demonstrating that the knockdown of POC1A expression inhibited the migration of lung cancer cells." (PMID 38429900, 2024). "Furthermore, the cell function experiments conducted in this study unequivocally demonstrated the capacity of POC1A in enhancing the proliferation, migration and invasion of lung cancer cells." (PMID 38429900, 2024).
serous ovarian cancer (1 paper, 2022). "POC1A was identified as a hub gene in high grade serous ovarian cancer through network analysis." (PMID 36338962, 2022).
triple-negative breast carcinoma (1 paper, 2025). An invasive breast carcinoma which is negative for expression of estrogen receptor (ER), progesterone receptor (PR), and human epidermal growth factor receptor 2 (HER2). "Based on the findings of this study, POC1A is considered to be an oncogene in triple-negative breast cancer." (PMID 40830747, 2025).
cancer (5 papers, 2019 to 2025). A tumor composed of atypical neoplastic, often pleomorphic cells that invade other tissues. "POC1 centriolar protein homolog A (POC1A), a centriolar protein involved in the formation of stable centrioles, has been associated with both cancer promotion and suppression in various malignant tumors." (PMID 40830747, 2025). "While existing studies have established an association between POC1A and cancer, its specific correlation with LUAD remains unexplored." (PMID 38429900, 2024). "Given POC1A’s role and prognostic value in pan-cancer, the possible biological function and associated signal pathway of POC1A in pan-cancer were further predicted using GSEA analysis." (PMID 35748773, 2022). "Based on these findings, elevated POC1A expression in pan-cancer was linked to a poor prognosis and might be a potential prognostic biomarker." (PMID 35748773, 2022). "Given that the aberrant regulation of the cell cycle is a fundamental characteristic of tumours and is intricately linked to cancer onset and progression, it is plausible that POC1A may play a role in driving the advancement of LUAD through its influence on the cell cycle." (PMID 38429900, 2024). "Researchers suggested that POC1A is a valuable biomarker in pan-cancer, whereas the impact of POC1A on EMT and its function in the development of TNBC remains uncertain." (PMID 40830747, 2025). "Recent studies have revealed a close association between heightened POC1A levels and poor prognosis across various cancers, positioning POC1A as an adverse prognostic marker in pan‐cancer." (PMID 38429900, 2024). "In our investigation, we observed an up‐regulation of POC1A expression across various cancer types, including LUAD." (PMID 38429900, 2024). "Recently, POC1 centriolar protein A (POC1A) has emerged as a potential biomarker for various cancers, contributing to cancer onset and development." (PMID 38429900, 2024). "RT‐qPCR analysis confirmed higher POC1A expression in tumour tissues compared to paired para‐carcinoma tissues." (PMID 38429900, 2024). "POC1A expression was negatively correlated with KIRP but positively correlated with can in 23 of 33 tumors, suggesting that high CNA was among the major reasons for high POC1A expression in pan-cancer." (PMID 35748773, 2022). "The POC1A expression in normal and tumor tissues underwent analysis in this study utilizing data from the Genotype-Tissue Expression (GTEx) project and the Cancer Genome Atlas (TCGA) database." (PMID 35748773, 2022). "The findings showed that POC1A was significantly highly expressed in 27 of 33 cancer types, while observed only in LAML, PCPG, and TGCT that POC1A expression was reduced." (PMID 35748773, 2022). "All of these findings imply that POC1A is an important oncogene and a potential biomarker for pan-cancer poor prognosis." (PMID 35748773, 2022). "Then, RT-qPCR was applied to analyze these genes, and POC1A was selected for its significantly high expression in adjacent tissues compared to cancer tissues." (PMID 33052878, 2020). "As the results of RT-qPCR, immunohistochemistry and several GEO datasets show, not only the mRNA expression but also the protein expression of POC1A is higher in cancer-adjacent tissues than in tumor tissues." (PMID 33052878, 2020). "The pan‐carcinoma analysis revealed up‐regulation of POC1A across most cancers." (PMID 38429900, 2024). "suggests that POC1A may influence tumour progression and represent a potential therapeutic target for cancer." (PMID 38429900, 2024). "POC1 centriolar protein A (POC1A) effect in pan-cancer remains uncertain." (PMID 35748773, 2022). "POC1A expression in pan-cancer was observed through TIMER2 webserver usage." (PMID 35748773, 2022). "In pan-cancer, POC1A relation with immune checkpoint gene expression was assessed." (PMID 35748773, 2022).
cancer (continued). "Besides, the infiltration levels of immune killer cells, including CD4 T and CD8 T cells and activated NK cells, were inversely correlated with POC1A expression in pan-cancer." (PMID 35748773, 2022). "Additionally, gene set enrichment analysis (GSEA) was utilized for exploring POC1A potential molecular mechanism in pan-cancer." (PMID 35748773, 2022). "In addition, TMB and MSI, as well as immune checkpoint genes in pan-cancer, were related to POC1A expression." (PMID 35748773, 2022). "It has been suggested that POC1A may be a target for cancer therapies." (PMID 40830747, 2025). "Based on the Reactome database, genes correlating with POC1A (P <0.05) were ranked and underwent GSEA analysis in pan-cancer." (PMID 35748773, 2022).